PDK1 (pyruvate dehydrogenase kinase 1)
Diseases named in the same sentence as PDK1 in open-access papers (continued):
Sharing a sentence is not in itself a finding about the gene and the disease.
osteosarcoma (continued). "Our studies indicate that PDK1 in OSCs controls their stemness, tumorigenicity, and energy metabolism, making it a promising osteosarcoma therapy target." (PMID 40730548, 2025). "Mitochondria-targeted polymeric micelles (OPDEA-PDCA) target mitochondria and induce mitochondrial oxidative stress via inhibition of pyruvate dehydrogenase kinase 1(PDHK1), leading to immunogenic pyroptosis in osteosarcoma cell lines." (PMID 41246345, 2025). "We also found that PDK1 is involved in various metabolic processes in osteosarcoma cells, including glycogenesis, nitrate metabolism, dysregulated metabolism, tetraenoid backbone biosynthesis, alanine aspartate, and glutamate metabolism." (PMID 40971960, 2025). "The study explores the prognostic significance and therapeutic potential of 3-phosphoinositide dependent protein kinase-1 (PDK1) in osteosarcoma." (PMID 40971960, 2025). "This study aims to investigate the expression and prognostic significance of PDK1 in osteosarcoma using bioinformatics analysis of publicly available datasets and experimental validation." (PMID 40971960, 2025). "This was accompanied by repressing OSC stemness in vitro, thus supporting the potential applicability of PDK1 inhibition in osteosarcoma treatment." (PMID 40730548, 2025). "In the metastatic osteosarcoma group, however, we have not found the significant correlation between the expression level of PDK1 and osteosarcoma’s prognosis." (PMID 40971960, 2025). "To explore PDK1’s control mechanisms, we identified DEGs in “PDK1-knockdown OSCs over control OSCs” and “OSCs over differentiated osteosarcoma cells” via RNA-seq." (PMID 40730548, 2025). "Future study should focus on further elucidating the molecular pathways regulated by PDK1 in osteosarcoma and exploring its potential in clinical applications to improve patient outcomes." (PMID 40971960, 2025). "This study screened osteosarcoma samples with complete clinical follow-up data, established a model of PDK1 and clinical prognosis of osteosarcoma, and evaluated the accuracy of the model." (PMID 40971960, 2025). "The specific role of PDK1 in osteosarcoma, particularly its impact on glycolytic metabolism and clinical outcomes, remains underexplored." (PMID 40971960, 2025). "The receiver-operating characteristic (ROC) curve was performed to evaluate the expression specificity of PDK1 in the survival status of osteosarcoma patients." (PMID 40971960, 2025). "In conclusion, in vivo assays revealed that TRIM17 positively regulates the activation of the AKT/mTOR signaling pathway via FTO-mediated PDK1 expression, thereby enhancing osteosarcoma growth." (PMID 41145484, 2025). "In vitro experiments demonstrate that silencing PDK1 impairs glycolysis, reduces proliferation, and induces apoptosis in 143B osteosarcoma cells." (PMID 40971960, 2025). "Based on that, combined with MTX-resistant mRNA and miRNA data, we established a new 4-gene prognostic signature for osteosarcoma, including two high-risk MTXDEGs (CPE, PDK1) and two low-risk MTXDEGs (LASP1, LACTB)." (PMID 37937197, 2023). "PDK1 expression was suppressed in DXR-resistant osteosarcoma cells, consistent with our experimental findings that PDK1 is downregulated in MTX-resistant osteosarcoma." (PMID 37937197, 2023). "PDK1 upregulation was detected in osteosarcoma, which elevated a proliferative capacity of osteosarcoma cells." (PMID 34630511, 2021). "A previous study revealed that gene PPARG, gene IGHG3, and gene PDK1 were correlated with osteosarcoma." (PMID 34188683, 2021). "To further determine whether the prognosis of PDK1 in pan-cancer is similar to that of PDK1 in osteosarcoma, we conducted pan-cancer analysis to evaluate the overall impact of PDK1 on patients with different types of tumors." (PMID 40971960, 2025). "PDK1 expression is closely associated with poor prognosis in osteosarcoma patients, especially those without metastasis." (PMID 40971960, 2025).
osteosarcoma (continued). "Furthermore, silencing PDK1 in osteosarcoma cells impaired glycolysis, reduced cell proliferation, and induced apoptosis, highlighting its potential as a therapeutic target in osteosarcoma treatment." (PMID 40971960, 2025). "Currently, although there have been reports on the role of PDK1 in osteosarcoma, there is no study on the association between PDK1 and glycolic metabolism in osteosarcoma." (PMID 40971960, 2025). "Furthermore, univariate and multivariate COX analyses showed that PDK1 was an independent prognostic factor in patients with osteosarcoma." (PMID 41145484, 2025). "Although we identified the PDK1–glycolysis–ATF3 axis as a key regulator of OSC properties and osteosarcoma malignancy, the precise mechanisms by which PDK1-glycolysis regulates ATF3 expression in OSCs remain unclear." (PMID 40730548, 2025). "Therefore, targeting PDK-1 is an attractive therapeutic target for osteosarcoma, and by inhibiting the function of PDK1, it can effectively inhibit the proliferation and metastasis of osteosarcoma cells." (PMID 40971960, 2025). "It showed that higher PDK1 expression correlated with shorter survival than those with lower PDK1 expression being the only gene correlating significantly with the prognosis of patients with osteosarcoma." (PMID 40730548, 2025). "Additionally, we conducted in vitro experiments to examine the effects of PDK1 silencing on glycolytic metabolism in osteosarcoma cells." (PMID 40971960, 2025). "Recent studies suggest that FTO may activate the AKT pathway by regulating the m6A modification of PDK1, but whether this mechanism is conconservative in osteosarcoma still needs to be verified." (PMID 41145484, 2025). "Therefore, the validation experiment analyzed the effect of silencing PDK1 on the metabolism of osteosarcoma cells." (PMID 40971960, 2025). "Simultaneously inhibiting PDK1 can induce apoptosis of osteosarcoma cells." (PMID 40971960, 2025). "Experimental also found that enforced expression of PDK1 promoted osteosarcoma cell proliferation." (PMID 40971960, 2025). "To further study the expression of PDK1 in osteosarcoma and normal tissues, we immediately analyzed the expression of PDK1 in osteosarcoma cells and normal osteoblasts cells, as well as the function of PDK1 in osteosarcoma cells." (PMID 40971960, 2025). "Targeting PDK1 could provide a novel therapeutic strategy for treating osteosarcoma and possibly other cancers." (PMID 40971960, 2025). "In this study, in order to more accurately predict the survival rates of osteosarcoma patients in one-year, three-years, and five-years, we integrated data on survival time, survival status, and five features including PDK1 expression to create a nomogram of patient survival rates." (PMID 40971960, 2025). "To validate our bioinformatics analyses of clinical osteosarcoma specimens, we cultured six osteosarcoma cell lines with varying tumor aggressiveness under tumorsphere conditions (for OSCs) and subsequently determined PDK1 mRNA levels." (PMID 40730548, 2025). "In one study, the modulation of mitochondria inducing osteosarcoma pyroptosis, through inhibiting the pyruvate dehydrogenase kinase 1 (PDHK1), was achieved by the polymer micelle of dichloroacetate, which promotes enhanced antitumor efficacy in combination with immunotherapy." (PMID 39209834, 2024). "In addition, the organic arsenic compound Aa-Z2 induces ROS accumulation by targeting pyruvate dehydrogenase kinase 1 (PDK-1) to induce osteosarcoma apoptosis." (PMID 37512503, 2023). "More importantly, targeting PDK-1 provided an attractive opportunity to develop osteosarcoma treatments, and a series of novel inhibitors have been designed and synthesized to inhibit osteosarcoma growth." (PMID 36611209, 2023).
osteosarcoma (continued). "Among the early stage of the energy metabolic pathway genes, PDK1 was the only gene that fulfilled the significantly upregulated in OSCs and the consistently correlated with poor prognosis in patients with osteosarcoma across cohorts, suggesting its potential role in osteosarcoma progression." (PMID 40730548, 2025). "Therefore, in this study, we synthesized a novel organic arsenical Aa-Z2 that tended to be less toxic than inorganic arsenic with the aim of targeting cancer metabolism and discovered that Aa-Z2 could suppress osteosarcoma growth by inhibiting PDK-1." (PMID 36611209, 2023). "Pyruvate dehydrogenase kinase 1 (PDK1), a key enzyme balancing glycolysis and OXPHOS, was upregulated in OSCs and correlated with poor prognosis in patients with osteosarcoma." (PMID 40730548, 2025). "ATF3 mRNA level was elevated in OSCs (GSE152048), and TARGET-OS analysis showed a positive correlation between PDK1 and ATF3 expression in patients with osteosarcoma." (PMID 40730548, 2025). "While further investigation is warranted, our findings position ATF3 as a key downstream effector in the PDK1-mediated regulation of OSC characteristics and osteosarcoma pathogenesis." (PMID 40730548, 2025). "Mechanistically, TRIM17 regulates FTO degradation via ubiquitination, modulates PDK1 gene methylation, and thereby activates the AKT/mTOR signaling pathway, promoting osteosarcoma malignancy." (PMID 41145484, 2025). "A study has shown that the cuproptosis-related genes LIAS, PDK1 and BCL2L1 were strongly related to immune cells infiltrating in osteosarcoma, serving as the reliable targets for predicting the patients’ immune response." (PMID 37380924, 2023). "Survival analysis demonstrated a significant negative correlation between high PDK1 expression and overall survival in osteosarcoma patients." (PMID 40971960, 2025). "It was found that compared with osteoblast cell hFOB1.19, PDK1 expression was significantly increased in osteosarcoma 143B and MG63, while PDK1 only slightly increased in U-2 OS, with original gel images showed in S2 File and data processing recorded in S9 Table." (PMID 40971960, 2025). "Although elevated PDK1 expression correlates with poor prognosis in osteosarcoma, this study does not establish PDK1 as a validated clinical biomarker." (PMID 40971960, 2025). "PDK1 was significantly upregulated in clinical osteosarcoma tissues compared to nontumor tissues in two bulk RNA-seq datasets (PRJNA539828, GSE126209)." (PMID 40730548, 2025). "Researchers have produced dichloroacetate polymer micelles (OPDEA-PDCA) that can induce mitochondrial oxidative stress by inhibiting pyruvate dehydrogenase kinase 1 (PDHK1), leading to GSDMD-mediated pyroptosis of osteosarcoma cells and enhancing osteosarcoma immunotherapy." (PMID 38304430, 2024). "In osteosarcoma tumor microenvironment-related literature, we take notice that the connection between the score of immunity and survival state has been investigated, and C3AR1, PPARG, PDK1, IGHG3, and C1Q are recognized as prognostic biomarkers." (PMID 36844870, 2023). "In conclusion, we speculate that the expression of PDK1 is negatively correlated with the overall sample of osteosarcoma and the prognosis of non-metastatic group." (PMID 40971960, 2025). "Mechanistically, TRIM17 promotes the ubiquitination and degradation of FTO protein, enhances PDK1 mRNA stability via N6-methyladenosine (m6A) modification, and subsequently promotes phosphorylation-dependent activation of the AKT/mTOR signaling pathway, thereby driving osteosarcoma malignancy." (PMID 41145484, 2025). "Therefore, PDK1 and PPARG may become prognostic genes in osteosarcoma and may be targets for subsequent regulation of ICI-related genes for osteosarcoma treatment." (PMID 39654890, 2024).
osteosarcoma (continued). "Therefore, our assayal results suggest that TRIM17 regulates the expression of PDK1 through FTO-mediated m6A demethylation in osteosarcoma, and further activates downstream AKT/mTOR signaling pathway activity to positively regulate the malignancy of osteosarcoma." (PMID 41145484, 2025). "The expression of PDK1 was significantly upregulated in 143B OSCs rather than in 143B non-OSCs, consistent with findings in the OSC population of primary osteosarcoma specimens, along with significant upregulation of stem cell markers, such as SOX2, KLF4, and ABCG1." (PMID 40730548, 2025).
acute myeloid leukemia (17 papers, 2007 to 2025). Acute myeloid leukemia (AML) is a group of neoplasms arising from precursor cells committed to the myeloid cell-line differentiation. "Of note, the association of PDK1 with unc-51-like autophagy-activating kinase 1 (ULK1) was shown to regulate autophagy in acute myeloid leukemia (AML) cell lines." (PMID 30250843, 2018). "Here, we show that Pyruvate dehydrogenase kinase 1 (PDK1) acts as a targetable determinant of different metabolic states in acute myeloid leukemia (AML)." (PMID 35232995, 2022). "Moreover, Dichloroacetophenone (DAP), a highly potent inhibitor of PDK1 has been showed earlier to have an inhibitory effect in acute myeloid leukemia." (PMID 28505181, 2017). "Whether targeting PDK1 with DAP can inhibit acute myeloid leukemia (AML) and how it works remains unknown." (PMID 26593251, 2016). "This leads to the downregulation of PDK1 expression, thereby suppressing both proliferation and glycolysis in acute myeloid leukemia (AML) cells and hindering AML progression." (PMID 41231037, 2025). "Previous studies have found that PDK1 is overexpressed in multiple myeloma (MM), acute myeloid leukemia (AML), breast invasive carcinoma (BRCA), and OS." (PMID 36276092, 2022). "PDK1, a downstream target of hypoxia inducible factor 1 alpha (HIF1α), is upregulated in a number of cancers including ovarian cancer (OCa), gastric cancer (GCa), colorectal cancer (CRCa), PCa, and acute myeloid leukemia (AML)." (PMID 33384955, 2020).
Insulin resistance (17 papers, 2015 to 2025). Increased resistance towards insulin, that is, diminished effectiveness of insulin in reducing blood glucose levels. "The study concludes that hesperidin has a significant preventative impact on insulin resistance caused by a high-fat diet through the activation of the IR/PDK1 pathway." (PMID 38234970, 2023). "Whereas, O-GlcNAcylation of several insulin-signaling key players (such as AKT, PT1B, and PDK1) has been shown to be associated with insulin resistance in the liver, the effect of the HBP on insulin signaling in the heart has not been adequately addressed." (PMID 30420836, 2018). "On the contrary, mutations within the PH domain of Akt and/or PDK1 can disrupt its ability to bind to PIP3, thereby suppressing its activation and downstream signalling, and driving the development of insulin resistance." (PMID 41032702, 2025). "Adipocyte-specific PDK1 knockout (A-PDK1KO) mice manifest symptoms of metabolic disease including insulin resistance, glucose intolerance, and hepatic steatosis that resembles the phenotype generated by knocking out the insulin receptor in adipocytes." (PMID 37941908, 2023). "Expression levels of Pla2g16 were downregulated after ω-3FA intake that was highly expressed in Hcy-induced insulin resistance mice while levels of PDK1 and Glut1 decreased." (PMID 33643070, 2021). "Pdk1-Foxo1 signaling also contributes to adipose inflammation and insulin resistance." (PMID 28514752, 2017). "Significantly improved insulin resistance by restoring hepatic FOXO1 nuclear translocation and upregulating gene expression of Akt2, Irs1, Irs2, Pi3kca, Pi3kcg and Pdk1." (PMID 25621503, 2015). "Though, this study did not directly address the effect of PKC activation on selective insulin resistance, contribution of endogenous glucose production is proposed in NOD individuals as a result of increased gene expression level of PDK1 in this group which is the main regulator of PKC axis." (PMID 32670384, 2020). "On the other hand, mice lacking 3-phosphoinositide-dependent protein kinase 1 (PDK1) in the myeloid cells, which are downstream signaling molecules in the IR/Irs2 pathway, showed adipose tissue inflammation and insulin resistance under the HF diet condition." (PMID 30451856, 2018). "However, additional investigations are necessary to determine whether ROCK directly phosphorylates PDK1 serine residues and ROCK-mediated PDK1 signaling defect may collaborate to develop insulin resistance." (PMID 34234788, 2021).
nasopharyngeal carcinoma (16 papers, 2014 to 2025). A carcinoma arising from the nasopharyngeal epithelium. "PDK1 is pivotal for proliferation of nasopharyngeal cancer cells via the Wnt/β-Catenin pathway." (PMID 39220137, 2024). "Experiments with hLf demonstrated the further downregulation of 3-phosphoinositide-dependent protein kinase 1 (PDK1) transcription via mitogen-activated protein kinase/c-Jun pathway following deactivation of AKT signaling leading to inhibition of nasopharyngeal carcinoma (NPC) tumorigenesis." (PMID 34201342, 2021). "In nasopharyngeal carcinoma, reduced PPP2R2B expression activates PDK1/MYC pathways to induce BEZ235 resistance." (PMID 27888627, 2016). "Reduced PTEN and PPP2R2B expression correlated with activated AKT/mTOR and PDK1/MYC pathways, which can confer considerable BEZ235 resistance in nasopharyngeal carcinoma." (PMID 25762617, 2015). "Reduced PTEN and PPP2R2B expression correlated with activated AKT/mTOR and PDK1/MYC pathways and conferred considerable BEZ235 resistance in nasopharyngeal carcinoma." (PMID 25762617, 2015). "Neoalbaconol, a terpenoid isolated from the fungus Albatrellus confluens, targets PDPK1/PDK1 (3-phosphoinositide-dependent protein kinase 1) and inhibits the subsequent PI3K-AKT signaling in the nasopharyngeal carcinoma (NPC) nude mouse model, resulting in activation of autophagy." (PMID 36497321, 2022). "In this study, using an integrated analysis of acquired BEZ235-resistant nasopharyngeal carcinoma cells, we demonstrate that DNA methyltransferase is a key modulator and a common node upstream of the AKT/mTOR and PDK1/MYC pathways, which are activated in cancer cells with acquired BEZ235 resistance." (PMID 25762617, 2015).